ALB (albumin)
Diseases named in the same sentence as ALB in open-access papers (continued):
Sharing a sentence is not in itself a finding about the gene and the disease.
malnutrition (continued). "The Glasgow Prognostic Score (GPS) has been reported as a parameter that elevated serum C-reactive protein (CRP) levels reflect a progression cancer stage, and decreased serum albumin levels are an indicator of malnutrition." (PMID 34519976, 2022). "Blood analyses specific to severe malnutrition include several parameters besides hemoglobin, albumin, and osteoporosis, according to a study done in the Clinical Unit of Nutrition-Eating Disorders in the Raymond Poincaré Hospital, France." (PMID 36286205, 2022). "Malnutrition has an impact on surgical incision healing, and serum albumin, TLC, hemoglobin, and age are mentioned in several studies as independent predictors of postoperative mortality." (PMID 35590357, 2022). "The factors that change with exacerbating inflammation and malnutrition (albumin, hemoglobin, neutrophil count, the NLR) affected the efficacy of the vaccination." (PMID 35327438, 2022). "The serum albumin level is also lower in patients with malignant tumors, severe tuberculosis, malnutrition, accumulation of thoracoabdominal fluid, kidney disease, and hypoalbuminemia." (PMID 36316884, 2022). "At the same time, the inflammatory response reduces albumin synthesis, further inducing malnutrition." (PMID 36562034, 2022). "Association-affecting variables, such as gender, age, time from injury to surgery, hemoglobin (Hb), total lymphocyte count (TLC), albumin, malnutrition, and co-morbidities, were recorded and analyzed." (PMID 35590357, 2022). "Based on laboratory parameters such as serum albumin, two studies have revealed a 2–3 times higher incidence of malnutrition in PJI patients than in those with aseptic loosening." (PMID 36297116, 2022). "Albumin and total lymphocyte count (TLC) are nutritional markers that can be used to define malnutrition when albumin is < 35 g/L and TLC is < 1.5 × 109 cells/L." (PMID 35590357, 2022). "Although ALB is recognized as an important marker for long-term malnutrition and systemic stress response, ALB levels are influenced by several factors." (PMID 36267459, 2022). "Meanwhile, a serum albumin level of <25 g/L, indicating severe malnutrition, has a greater impact on the amputation rate of DFU." (PMID 36472981, 2022). "The weight, BMI, handgrip strength, gait speed, hemoglobin, serum albumin, and lymphocyte count were significantly lower in the malnutrition group than in the non-malnutrition group." (PMID 35990353, 2022). "The degree of malnutrition in patients with CKD was negatively correlated with the expression levels of serum ALB (r = −0.188), serum PA (r = −0.237) and Hb (r = −0.174) by using spearman correlation analysis (P < 0.05)." (PMID 36687720, 2022). "In both males and females, the BMI, PhA, and HGB and ALB levels decreased as the severity of malnutrition worsened, while the PLT count increased (p < 0.05)." (PMID 35684060, 2022). "In elderly patients receiving MHD, medical staff should pay increased attention to patients with older age, lower educational level, lower level of social support, and malnutrition and monitor their albumin level and calf circumference." (PMID 35366144, 2022). "Patients presenting with a ‘triple low’ preoperative state (anaemia {low haemoglobin}, malnutrition {low albumin}, and deconditioned {low functional capacity, e.g. low peak VO2}) are at greatest risk of postoperative complications and death." (PMID 35614461, 2022). "DM patients with malnutrition features such as low serum albumin have more comorbidities, including dementia." (PMID 36344933, 2022). "Low serum albumin always indicates malnutrition, which is more common in patients with DFU given elevated flux and poorly controlled blood glucose." (PMID 36472981, 2022). "As a significant transport protein synthesized in the liver, serum albumin was widely utilized to assess the nutritional state and diagnose malnutrition." (PMID 35923200, 2022).
malnutrition (continued). "A recent study found little overlap in malnutrition identified by serum albumin or total lymphocytes alone in patients undergoing total knee arthroplasty, questioning their predictive value as proxies for malnutrition." (PMID 36297116, 2022). "Low albumin content is believed to result from malnutrition on the one hand and inflammation on the other." (PMID 35327438, 2022). "In our study, increased adherence to the Mediterranean diet resulted in decreased systolic blood pressure, decreased malnutrition inflammation score, increased serum albumin, and increased serum magnesium." (PMID 36233612, 2022). "Markers of malnutrition, in which normalized protein catabolic rate (nPCR) and serum albumin were assessed during the ascertainment period, were inversely related to the study outcome." (PMID 37674993, 2022). "Hypoalbuminemia is associated with a higher risk of nutritional impairment, lower overall survival and higher inflammatory markers (e.g., CRP) since inflammation and malnutrition decrease albumin concentration by reducing albumin synthesis." (PMID 36145174, 2022). "Serum albumin levels, as an excellent indicator of malnutrition and cachexia, have been widely used in various advanced cancers." (PMID 34996395, 2022). "Not only malnutrition but also systemic inflammatory responses contribute to a decrease in the albumin levels in serum, leading to a poor prognosis for COPD patients." (PMID 36522751, 2022). "The key findings were significantly greater NRS-2002 scores (i.e., increased risk of malnutrition) in those who were older, had higher BUN levels, or had lower albumin or hematocrit levels." (PMID 36320896, 2022). "Patients aged > 55 years were more likely to have DM (58.3%), CVD (69.96%), COPD (17.94%), malnutrition (albumin level 3.71 g/dL), and a higher proportion of AVG and Perm-catheter for dialysis vascular access (19.38% vs. 2.1%, p < 0.05) than those ≤ 55 years." (PMID 36084024, 2022). "Low albumin is an indicator of malnutrition, and preoperative hypoalbuminemia is often seen in patients with advanced GC." (PMID 34519976, 2022). "Serum TP and ALB are regarded as the important indicators of the protein metabolism, and decreased serum TP and ALB concentrations is usually related to malnutrition and growth retardation in animals." (PMID 35968000, 2022). "It should be pointed out that serum albumin has only the prognostic value of malnutrition prevalence." (PMID 35276861, 2022). "It is also able to detect risks of malnutrition before the severe change in individuals’ weight or serum albumin occurs." (PMID 36411835, 2022). "Firstly, serum albumin is correlated with the nutritional condition of older people, and persistent malnutrition plays a vital role in cognitive impairment." (PMID 36497797, 2022). "Serum albumin level and BMI are well-known markers of malnutrition, and the relationship between malnutrition and total mortality has been reported in older people." (PMID 35268404, 2022). "Among them, a low serum albumin level (<35 g/L) is considered one of the simplest and most widespread markers of malnutrition." (PMID 36684164, 2022). "The results showed that curcumin treatment significantly improved the malnutrition status; serum total protein, albumin, cholesterol, and triglyceride levels were higher than those in the model group." (PMID 35132306, 2022). "When patients suffer from malnutrition, their energy, protein, or amino acid supply is reduced, their albumin synthesis rate slows down, and serum albumin concentrations decrease." (PMID 36684164, 2022). "Albumin is the most commonly used marker of protein nutritional status, and albumin concentration is reduced by malnutrition and inflammation." (PMID 35276996, 2022). "Both CRP and albumin are widely used as acute inflammatory markers in clinical settings, and albumin is also used as a marker of malnutrition." (PMID 35094678, 2022).
malnutrition (continued). "The most significant association was found between total protein levels and risk of malnutrition; albumin levels and cognitive impairment, ADL and IADL, frailty, sarcopenia, and the risk of malnutrition." (PMID 35805838, 2022). "The expression levels of ALB, PA and Hb in the malnutrition group were significantly lower than those in the normal group (P < 0.05)." (PMID 36687720, 2022). "The MNA long-form had adequate predictive ability of markers of malnutrition as compared to serum albumin concentration level, among the elderly community population." (PMID 36411835, 2022). "Albumin is an important component in human plasma and a good indicator of liver dysfunction and malnutrition." (PMID 35481993, 2022). "Malnutrition and risk of malnutrition were defined as MNA < 17, albumin < 3.5 g/dL and 17 ≤ MNA ≤ 24, 3.5 g/dL ≤ albumin < 3.9 g/dL, respectively." (PMID 36687683, 2022). "The reduction of micronutrients (vitamin A, calcium, and albumin) in the current study is consistent with several studies which have associated HIV and helminth infections with malnutrition." (PMID 36501001, 2022). "Others prospective studies and surgical evidence have demonstrated a correlation between albumin count, malnutrition, and survivals." (PMID 36286210, 2022). "The level of serum albumin was a sensitive and valuable indicator which can indicate malnutrition in EC patients." (PMID 36337651, 2022). "In that study, the median value of serum albumin in the cohort was 3.3 g/dL, which suggests that there were fewer patients with malnutrition than in our cohort." (PMID 36654553, 2022). "Our short and long-term follow-up did not reveal any modified outcomes with regard to decreased serum albumin, type of surgery, age, malnutrition, or fluid administration, confirming the heterogeneity of factors in overall cancer mortality." (PMID 35329082, 2022). "Several blood biomarkers, in addition to albumin, can be useful biochemical indicators to characterize malnutrition, even in the presence of chronic inflammation (e.g., pre-albumin, hemoglobin, total cholesterol, and total protein)." (PMID 35813046, 2022). "Severe malnutrition (albumin < 2.1 g/dL) was observed in two patients on the first day (1% of patients)." (PMID 36558522, 2022). "Different from these inflammatory parameters, albumin is one of the nutritional indicators, and malnutrition weakens the immunological and phagocytosis mechanisms of the human body, increasing the risk of infection and other diseases." (PMID 36460981, 2022). "The low albumin usually represented severe malnutrition in cancer patients, and the patients were generally in poor condition with serious symptoms and more malignant tumors." (PMID 36684195, 2022). "Albumin was a routine hematological indicator of malnutrition biomarker, and patients were considered malnourished when their serum albumin <35 g/L." (PMID 35721788, 2022). "Low serum albumin levels are generally regarded as an indicator of severe inflammation or malnutrition." (PMID 35814479, 2022). "For malnutrition, albumin is an important nutritional marker in patients with gastrointestinal cancer." (PMID 36212479, 2022). "Serum albumin is considered a biomarker of malnutrition–inflammation syndrome, and there is emerging data that hypoalbuminemia is related to worse survival in intensive care unit patients." (PMID 35297102, 2022). "Malnutrition is partially reflected by a lower albumin concentration and can impair the antitumor immune response, increase susceptibility to infection and postoperative complications, and influence the intensity of treatment that a patient can tolerate." (PMID 36230814, 2022). "Low PA was observed among albumin levels below 3.5 g/dl and vegetarian patients, which is likely due to malnutrition, which is very common in India." (PMID 35842730, 2022). "Inflammation contributes to decreased serum albumin levels and is connected with malnutrition, inflammation and atherosclerosis (MIA) syndrome." (PMID 36558511, 2022).
malnutrition (continued). "Biochemical parameters showed decreased albumin levels in patients with malnutrition using GLIM and SPA criteria." (PMID 35158762, 2022). "In patients with malignant tumors, the serum albumin level tends to decrease because of malnutrition and systemic inflammatory responses." (PMID 36054114, 2022). "Serum ALB levels reflect patients' nutritional status; a low serum ALB level indicates a state of malnutrition." (PMID 36704518, 2022). "Simple biochemical parameters, such as albumin, hemoglobin, and TLC have long been identified as risk indicators of malnutrition-related complications." (PMID 35755035, 2022). "In a locally advanced and/or metastatic setting, serum albumin level diminishes independently in the presence of malnutrition." (PMID 35173556, 2022). "Blood tests should include short-term indices of malnutrition, such as prealbumin and cholinesterase, and long-term indices, such as serum albumin." (PMID 36235705, 2022). "Both risk of malnutrition and malnutrition assessed by the MNA and serum albumin level was associated with all-cause mortality." (PMID 36687683, 2022). "On this account, a new biomarker, the fibrinogen to albumin ratio, was implemented to determine medical conditions including malnutrition, coagulation system, systemic inflammation, and hepatic insufficiency." (PMID 35887976, 2022). "Numerous reports have demonstrated that albumin is a strong predictor for outcome across the spectrum of HF and provides comparable prognostic information to simple or multidimensional malnutrition tools." (PMID 35352504, 2022). "The CRP/ALB ratio, a combined index of the ALB and CRP levels, is known to be related more consistently to prognosis than a single marker, accurately reflecting the degree of inflammation or nutritional deficiency." (PMID 36704518, 2022). "The proportions of patients having malnutrition were 10.7%, 55.8%, and 27.2% according to albumin, prealbumin, and total lymphocyte count, respectively." (PMID 33800823, 2021). "There is also evidence that serum albumin concentrations can serve as a valuable predictor of nutritional status in cancer patients, and malnutrition is correlated with poor survival." (PMID 33866376, 2021). "Historically, albumin and other serum proteins have been widely used by physicians as biomarkers of malnutrition." (PMID 34660664, 2021). "In this study, DMD-delE51 pigs showed decreased gastric fundic gland and intestinal wall thickness, shortened intestinal villus height, reduced levels of ALB, PA, glycogen and triglyceride, similar to clinical manifestations of malnutrition in human patients." (PMID 34266495, 2021). "The relation to albumin concentration can be explained by the already mentioned possible higher concentration of des-acyl ghrelin and low plasma levels of acyl ghrelin what may contribute to malnutrition and this is associated with a poorer nutritional status in advanced stages of CKD." (PMID 34959967, 2021). "Pearson’s correlation analysis indicated the specific bacterial abundances were associated with the malnutrition-associated phenotype e.g., body weight, CRL, total protein, albumin and creatinine." (PMID 33914799, 2021). "Patients with high risk of malnutrition were dominant in men, more CTP class B/C, more alcoholism, more ascites, lower BMI, more sarcopenia, more visceral adiposity, lower albumin, higher creatinine, and PT-INR." (PMID 34901116, 2021). "When considering further validation of albumin as a biomarker of nutritional status, utilizing a population with expected higher rates of malnutrition would be advocated." (PMID 33673556, 2021). "The relationship between albumin and malnutrition becomes further complicated in patients with end-stage organ disease or chronic inflammatory conditions." (PMID 33592030, 2021). "Decreased serum albumin is usually an indicator of malnutrition or combined chronic wasting disease." (PMID 33833359, 2021).
malnutrition (continued). "These two studies suggest that malnutrition in obese people mainly manifested in low serum albumin levels, which has been shown to reflect active systematic inflammation." (PMID 34977188, 2021). "The synthesis of albumin is suppressed by inflammation and malnutrition, and therefore serum albumin concentration can reflect both the systemic inflammatory response in a patient and can be used as a simple indicator of a patient’s nutritional condition." (PMID 34885242, 2021). "The relationship between malnutrition (reflected by BMI and serum albumin level) and cancer prognosis has also been extensively assessed for various cancers." (PMID 34660250, 2021). "Onodera’s PNI is a useful indicator for malnutrition that can be calculated from only the serum albumin level and blood lymphocyte count." (PMID 33918066, 2021). "Another possibility is that serum albumin can reflect the nutrition status of patients; lower serum albumin is often an indicator of malnutrition." (PMID 34869630, 2021). "There are studies regarding loss of weight, sarcopenia, low body mass index and low serum albumin to define malnutrition in patients with malignancy." (PMID 33957727, 2021). "Preoperative blood test showed liver disorder (AST 42 U/I, ALT 87 U/I), malnutrition (ALB 3.0 g/dl, pre-albumin 15.6 mg/dl, retinol binding protein (RBP) 2.4 mg/dl) and anemia (Hb 8.4 g/dl)." (PMID 34061274, 2021). "The proportions of patients having malnutrition were 10.7%, 55.8%, and 27.2% according to albumin, prealbumin, and total lymphocyte counts, respectively." (PMID 33800823, 2021). "Age, female sex, chewing problems, malnutrition, polypharmacy, low Mini-Mental Status Examination (MMSE) score, depressed mood, low serum albumin, and functional constipation were associated with anorexia in the univariate analysis." (PMID 34071957, 2021). "As the most commonly used biomarker of malnutrition, serum ALB level < 33 g/L was found to be a significant predictor for early mortality." (PMID 34271974, 2021). "Malnutrition and lower levels of serum albumin were excluded from the multivariate analysis because they are consequences of anorexia of aging rather than the causes." (PMID 34071957, 2021). "Accordingly, systemic inflammation is considered to exacerbate malnutrition via low serum albumin levels in patients with malignancy." (PMID 33507925, 2021). "The database we used included multiple inflammatory variables, including albumin adjusted for CRP level in order to take into account malnutrition with a view to ensuring model robustness." (PMID 34284784, 2021). "Serum albumin is a known biochemical marker for malnutrition in predicting perioperative complications in head and neck surgery, although the direct relationship between hypoalbuminemia and infection in free-flap reconstruction is unclear." (PMID 33925543, 2021). "In this respect, some studies have already shown that BCAAs apparently increases albumin levels in older persons suffering from malnutrition." (PMID 33800577, 2021). "The risk of malnutrition was higher in an older female with a lower MMSE score, BMI, and serum albumin concentration (P < 0.001)." (PMID 34880747, 2021). "One of the useful indicators for evaluating nutritional status is albumin level, and malnutrition can be diagnosed with low serum albumin level." (PMID 34903980, 2021). "In Vietnam, a retrospective cohort study in Ho Chi Minh City on 459 patients with gastrointestinal cancer reported a malnutrition prevalence of 19% based on the measurement of body mass index (BMI) and serum albumin level." (PMID 33800823, 2021). "Recently, low albumin levels have been regarded as more of a disease severity marker than as a marker of malnutrition, when such low levels are detected upon admission to hospital." (PMID 34207873, 2021). "Upon admission, 7 patients (9.59 %) had malnutrition: 4 with BMI < 18.5 kg/m2 and 3 with serum albumin < 35 g/l." (PMID 34496796, 2021).